PDP2 (pyruvate dehydrogenase phosphatase catalytic subunit 2)
Description:
Mitochondrial enzyme that catalyzes the dephosphorylation and concomitant reactivation of the alpha subunit of the E1 component of the pyruvate dehydrogenase complex (PDC), thereby stimulating the conversion of pyruvate into acetyl-CoA (By similarity). Acts as a crucial regulator of T cell metabolism and function, with a particular focus on T-helper Th17 (By similarity).
Synonyms: PDPC 2; KIAA1348; PPM2C2; PPM2B
Tractability: PROTAC: ubiquitination databases record sites on it; its protein half-life has been measured.
Gene: Protein-coding gene on chromosome 16 (66,878,589 to 66,895,754, forward strand). Ensembl gene ENSG00000172840.
Subcellular location: Mitochondrion
Subcellular location (Human Protein Atlas): Mitochondria
Pathways (Reactome):
Metabolism: Regulation of pyruvate dehydrogenase (PDH) complex
Gene Ontology:
Molecular function: [pyruvate dehydrogenase (acetyl-transferring)]-phosphatase activity; cation binding; protein serine/threonine phosphatase activity
Biological process: T-helper cell differentiation
Cellular component: mitochondrion; mitochondrial matrix
Genetic constraint (gnomAD): Loss-of-function variants: 26 observed, 37.54 expected, observed/expected ratio (o/e) 0.69, 90% interval 0.51 to 0.96. The upper end of that interval is the gene's LOEUF score, 0.96, which puts it in group 4 of 6, group 1 being the genes least tolerant of losing a copy. Missense variants: 571 observed, 693.79 expected, observed/expected ratio (o/e) 0.82, 90% interval 0.77 to 0.88. Synonymous variants: 275 observed, 285.37 expected, observed/expected ratio (o/e) 0.96, 90% interval 0.87 to 1.07.
Homologues: Orthologues: chimpanzee PDP2 (99% identical), macaque PDP2 (99% identical), dog PDP2 (88% identical), pig PDP2 (88% identical), guinea pig PDP2 (87% identical), mouse Pdp2 (85% identical), rabbit PDP2 (84% identical), rat Pdp2 (82% identical), zebrafish pdp2 (51% identical), tropical clawed frog pdp2 (46% identical), Drosophila melanogaster Pdp (35% identical), Caenorhabditis elegans pdp-1 (29% identical), and 7 more. Paralogues in human: PDP1 (49% identical), PPM1M (18% identical), PPM1H (18% identical), PPM1F (17% identical), PPM1J (17% identical), PPM1L (16% identical), PPM1N (16% identical), PPM1E (16% identical), PPM1B (16% identical), PPM1G (15% identical), PPM1A (15% identical), PPM1K (14% identical), and 4 more.
Diseases named in the same sentence as PDP2 in open-access papers:
PDP2 is named in the same sentence as 14 diseases in open-access papers, as found by Europe PMC text mining. Sharing a sentence is not in itself a finding about the gene and the disease. The quoted sentences say what the papers report.
melanoma (3 papers, 2018 to 2025). A malignant, usually aggressive tumor composed of atypical, neoplastic melanocytes. "In SOX2-silenced control and acidic melanoma cells, we observed reduction of PDP2 and an appreciable increase of PDK1, suggesting an impaired mitochondrial OxPhos." (PMID 30466459, 2018). "In addition, PDK1 depletion, although present only in HLA-B,C-specific mAb B1.23.2-treated A375-M6 melanoma cells, together with an increase of PDP2, might have a role in triggering a cellular phenotype associated with an enhanced oxygen consumption rate." (PMID 31454998, 2019). "Additionally, the expression level of PDP2 was upregulated without any detectable change in the expression of PDK1 in FO-1β2 melanoma cells incubated with the HLA-B,C-specific mAb B1.23.2." (PMID 31454998, 2019).
breast carcinoma (2 papers, 2024 to 2025). "PDP2 expression is associated with the prognosis of breast cancer, and PDP2 dephosphorylation inhibits ACSL4 activity, inducing ferroptosis in tumor cells." (PMID 40746885, 2025). "PDP2 is highly expressed in breast cancer tissues and is significantly correlated with patient prognosis." (PMID 40746885, 2025). "Therefore, further research is essential to clarify the role of PDP2 in the progression of breast cancer." (PMID 40746885, 2025). "Consequently, further research is necessary to elucidate the role of PDP2 in breast cancer progression." (PMID 38466744, 2024).
prostate carcinoma (2 papers, 2022 to 2025). A carcinoma that arises from epithelial cells of the prostate gland. "In prostate cancer patients, the metabolic gene PDP2 associated with metastasis was identified through the analysis of circulating tumor cells (CTC) biofunctional." (PMID 40746885, 2025). "PDP2 is associated with the prostate cancer metastatic process." (PMID 40746885, 2025). "Correlation between clinical and pathological variables and PDHA1, PDP1 and PDP2 protein expression in prostate cancer." (PMID 35692804, 2022).
Barth syndrome (1 paper, 2025). Barth syndrome (BTHS) is an inborn error of phospholipid metabolism characterized by dilated cardiomyopathy (DCM), skeletal myopathy, neutropenia, growth delay and organic aciduria. "The table summarizes key differences between PDP1 and PDP2, including their expression patterns across tissues, regulatory features, and known associations with disease states such as cancer, traumatic brain injury (TBI), cardiomyogenesis defects, and Barth syndrome." (PMID 40491447, 2025).
hepatoma (1 paper, 2023). "TCDD dose-dependently induced Pdk4 and repressed Pdp2, while estrogen-related receptor γ (ERRγ) was induced which is associated with the induction of PDK4 in hepatoma cell lines under hypoxic conditions." (PMID 36914879, 2023).
lung carcinoma (1 paper, 2024). "There are no reports on PDP2 in ovarian cancer, and the scarce evidence on its roles in controlling metabolism is coming from a limited number of studies, mainly in prostate and lung cancer." (PMID 39086481, 2024).
neuroblastoma (1 paper, 2025). Neuroblastoma (NB) is the most common solid, extracranial childhood tumor. "GRP-R regulates glucose metabolism in neuroblastoma by modulating HIF-1α, PDK4, and PDP2." (PMID 40746885, 2025).
non-small cell lung carcinoma (1 paper, 2025). A group of at least three distinct histological types of lung cancer, including non-small cell squamous cell carcinoma, adenocarcinoma, and large cell carcinoma. "In A549 non-small cell lung cancer (NSCLC) cell line, muscle larva excretory/secretory products (ML-ESPs) induced the transcription of glucose metabolism reprogramming-related genes, and PDP2 was significantly upregulated." (PMID 40746885, 2025).
cancer (5 papers, 2018 to 2025). A tumor composed of atypical neoplastic, often pleomorphic cells that invade other tissues. "PDP2 is the activator of pyruvate dehydrogenase (PDH), and the function of PDH in the cancer-associated fibroblasts was demonstrated essential for the migration ability of the co-cultured cancer cells." (PMID 29954422, 2018). "PDK1, PDK2, PDK3, PDK4, PDP2, and PDPR genes can regulate the glucose metabolism and glycolysis of cancer cells." (PMID 34199666, 2021). "Cancer cells can evade such a response, as they activate pyruvate dehydrogenase kinase 1 (PDK1) or inhibit pyruvate dehydrogenase phosphatase catalytic subunit 2 (PDP2), resulting in limited pyruvate utilization by mitochondria and reduced ROS production." (PMID 29219147, 2018).
infection (3 papers, 2018 to 2022). The state of being infected such as from the introduction of a foreign agent such as serum, vaccine, antigenic substance or organism. "It is also apparent from our results that in addition to the expression of the PFKFB3 gene, infection of hSMs with the UT127 strain also induced higher levels of HIF1A, HK1, HK2, PDP1, and PDP2 genes compared with the infection with UT205." (PMID 35163725, 2022).
tumor (3 papers, 2019 to 2025). "The fact that tumor-associated PDHE1 subunit phosphorylation was unaffected by diet was consistent with this notion of direct enzymatic inhibition rather than the more indirect inhibition resulting from changes in stimulatory PDP2 phosphatase and inhibitory PDK1 kinase." (PMID 31242205, 2019). "PDP2 plays an important role in tumor metabolic reprogramming, regulating the growth and survival of cancer cells." (PMID 40746885, 2025). "PDP2 induces ferroptosis in tumor cells by dephosphorylating and inhibiting the Acyl-CoA Synthetase Long-Chain Family Member 4 (ACSL4) activity." (PMID 40746885, 2025). "Together, these results provide a platform for antigenic target identification using tumor-isolated B cells and protein arrays, and reveal CCDC155, PDP2 and GRB2 as the tumor-expressed target antigens recognized by Ab36, Ab73 and Ab89, respectively." (PMID 39086481, 2024).
metabolic disease (1 paper, 2025). A congenital disorder (due to inherited enzyme abnormality) or acquired (due to failure of a metabolically important organ) disorder resulting from an abnormal metabolic process. "While alterations in PDP1 expression or activity typically result in muscle and neurological pathologies, the dysregulation of PDP2 is more associated with liver-specific metabolic disorders, such as non-alcoholic fatty liver disease and insulin resistance." (PMID 40491447, 2025). "While both PDP1 and PDP2 are involved in PDH activation, PDP1 more substantially impacts PDH activity and thus has been more directly linked to metabolic diseases." (PMID 40491447, 2025).
PDP2 also shares sentences with these, for which no sentence is quoted: heart failure (1 paper); ovarian carcinoma (1).